U3 (Small nucleolar RNA U3 )
Synonyms: LOC124900922
Gene: Small nucleolar RNA gene on chromosome 4 (158,700,691 to 158,700,909, forward strand). Ensembl gene ENSG00000271817.
Gene Ontology:
Biological process: RNA processing
Cellular component: nucleolus
Homologues: Orthologues: chimpanzee U3 (99% identical), macaque U3 (86% identical). Paralogues in human: SNORD3E (79% identical), SNORD3P1 (79% identical), SNORD3G (77% identical), U3 (77% identical), U3 (75% identical), U3 (74% identical), U3 (73% identical), U3 (72% identical), SNORD3D (72% identical), U3 (71% identical), U3 (70% identical), SNORD3H (70% identical), and 10 more.